CXCR5 (C-X-C motif chemokine receptor 5)
Diseases named in the same sentence as CXCR5 in open-access papers (continued):
Sharing a sentence is not in itself a finding about the gene and the disease.
tuberculosis (9 papers, 2014 to 2025). A chronic, recurrent infection caused by the bacterium Mycobacterium tuberculosis. "Tfh cells have been shown to mediate protective immunity against tuberculosis via accumulation in infected lungs and production of proinflammatory cytokines, while mice deficient in Cxcr5 had increased susceptibility to Tbc due to defective T cell localization within the lung parenchyma." (PMID 36761174, 2022). "In experimental models, the data uncovered that CXCR5 is expressed on T cells to ensure their proper localization within tuberculosis granulomas and promote effective macrophage activation to elicit a full defense against Mtb infection." (PMID 37626620, 2023). "However, the absolute number and the frequency of Th1 cells within the CD45RA–CCR7+CXCR5+ CD4+ T cells compartment were significantly lower in patients with tuberculosis when compared to a healthy control, while the relative number of Tfh2 cell was increased." (PMID 36761174, 2022). "The absence of CXCR5/CXCL13 axis can lead to increased susceptibility to tuberculosis." (PMID 40264781, 2025). "For instance, CXCL13 promotes the recruitment of CXCR5+ follicular B- and T helper cells into the M. tuberculosis–infected lung, where they form ectopic lymphoid follicles that support protective immunity against TB." (PMID 34561226, 2021). "To study the distribution of Tfh cells in TB infections, we examined Mtb antigen-specific induction Tfh cells subsets (defined as CD4+ CXCR5+ PD-1+ ICOS− or CD4+ CXCR5+ PD-1− ICOS+ or CD4+ CXCR5+ PD-1+ ICOS+) in PTB and LTB individuals in an area highly endemic for tuberculosis." (PMID 25343703, 2014).
atherosclerosis (8 papers, 2020 to 2023). A disease characterized by the build-up of fatty material and calcium deposition in the arterial wall resulting in partial or complete occlusion of the arterial lumen. "A recent study has shown that high glucose accelerates atherosclerosis by SNO-GNAI2 coupling with CXCR5, activating the HIPPO/YAP pathway." (PMID 37759984, 2023). "CXCR5 is the receptor for CXCL13, and both the deficiency of CXCR5 and CXCL13 have been shown to attenuate atherosclerosis, thus underscoring a clear role for CXCL13 signaling in atherosclerosis." (PMID 34948275, 2021). "However, the role of CXCR5 in endothelial cells and in the process of atherosclerosis is largely unknown." (PMID 34294713, 2021). "Second, although we carried out many validations in other expression datasets and patients, the mechanism of CXCR5 leading to atherosclerosis and plaque vulnerability remains unclear and needs further verification through more detailed in vivo and in vitro experiments." (PMID 33052139, 2020). "G-protein alpha-i2, coded by GNAI2, is related to chemokine receptor signaling, including CXCR5 signaling, which is thought to induce Hippo/YAP-dependent DM-accelerated atherosclerosis." (PMID 36077273, 2022). "While many immune pathways were enriched in the upregulated DEGs (e.g., CXCR5, IL21R, CCR7 and CD22) (A,C), pathways such as “lipid and atherosclerosis’ and “fluid shear stress and atherosclerosis” were enriched in the downregulated DEGs (such as NOS3, KLF2 and KLF4)." (PMID 37218991, 2023).
Burkitt lymphoma (8 papers, 2010 to 2025). A rare form of malignant mature B-cell non-Hodgkin lymphoma. "CXCR5 is also named Burkitt's lymphoma receptor 1 because it was initially isolated from Burkitt's lymphoma and its expression is detected on tonsillar B cells as well as in all peripheral blood." (PMID 35702353, 2022). "CXCL13 is the sole ligand for the 7 transmembrane-domain G protein-coupled chemokine receptor CXCR5, which was originally cloned from a Burkitt’s lymphoma cDNA library and named BLR-1 (Burkitt`s lymphoma receptor-1)." (PMID 33732259, 2021). "CXCR5 was first reported from human Burkitt's lymphoma, whereafter the murine homologue of CXCR5 was cloned and its expression was found in a pattern similar to human CXCR5." (PMID 20504365, 2010). "CXCR5, originally named Burkitt lymphoma receptor 1 (BLR1), is upregulated in Burkitt lymphoma." (PMID 40427609, 2025). "CXCR5 regulates Burkitt’s lymphoma (BL) lymphomagenesis, B cell differentiation, and migration." (PMID 34947813, 2021). "The human Burkitt's lymphoma cell line NC-37, which expresses CXCR4, CXCR5, CXCR7 and CCR7, was selected as a model system." (PMID 21672222, 2011).
chronic hepatitis B (8 papers, 2011 to 2022). "It was reported that circulating CXCR5+CD4+ T cells were expanded in patients with chronic hepatitis B and high frequency of circulating CXCR5+CD4+ T cells were associated with HBeAg seroconversion through IL-21 production manner." (PMID 27447555, 2016). "This study examined whether the frequency of CD4+CXCR5+ TFH cells could be associated with active immunity in chronic hepatitis B (CHB) patients." (PMID 21750724, 2011). "High levels of CXCL13 in patients with chronic hepatitis B stimulated the recruitment of CXCR5+ CD8+ T cells to produce high levels of HBV-specific interferon-γ and IL-21 in patients with chronic HBV infection to improve viral control." (PMID 35844446, 2022). "Numbers of IL-21-producing CD8+CXCR5+ T cells are significantly increased in chronic hepatitis B (CHB)." (PMID 31663864, 2019). "Interestingly, the percentages of CXCR5+CD4+ T cells were greater in the HBeAg - positive chronic hepatitis B group than in the HC group (p < 0.05)." (PMID 24655429, 2014).
leukemia (8 papers, 2017 to 2023). A malignant (clonal) hematologic disorder, involving hematopoietic stem cells and characterized by the presence of primitive or atypical myeloid or lymphoid cells in the bone marrow and the blood. "At day 21 after leukemia cell transfer, we found a strong depletion of Eμ-Tcl1 cells, endogenous B cells, and CXCR5+CD4+ T cells in the spleens of the mCXCR5 CAR group compared to the control." (PMID 33431832, 2021). "To overcome the limitations of a xenotransplantation mouse model, we generated an anti-murine CXCR5 CAR construct that endowed murine T cells with specific activity against murine leukemia and primary B cells." (PMID 33431832, 2021). "For example, gene-modified cells could overexpress CXCR5 for homing to B cell follicles or apply lessons from graft-versus-leukemia studies in the cancer field to better understand potential graft-versus-viral reservoir effects." (PMID 37207227, 2023). "BETi synergized with anti-PD1 in vivo, resulting in the reduction of circulating leukemia cells, enrichment of CD8+ T cells in the bone marrow, and increase in expression of Tcf7, Slamf6, and Cxcr5 in CD8+ T cells." (PMID 36681742, 2023). "miR-494-3p was mainly paired with immune genes (CD3G, CXCL13, CXCR5, KLRC4), some of which had been annotated as oncogenes in leukemia including IGF1 (DRG; pan-cancer), IKZF3 (driver; leukemia), NABP1 (oncogene; leukemia), and PDGFRA (oncogene; pan-cancer)." (PMID 32605588, 2020). "Eμ-Tcl1 Tg leukemias exhibited heterogeneous surface staining for CXCR4, CXCR5 and CCR7, but were negative for CXCR3." (PMID 27843137, 2017).
non-small cell lung carcinoma (8 papers, 2014 to 2025). A group of at least three distinct histological types of lung cancer, including non-small cell squamous cell carcinoma, adenocarcinoma, and large cell carcinoma. "In a phase I clinical trial assessing the impact of CXCR5-modified CAR T cells targeting EGFR in advanced non-small cell lung carcinoma (NCT05060796), patients exhibited favorable tolerance to the treatment." (PMID 38903504, 2024). "A previous study focused on non-small-cell lung cancer also similarly found that CXCR5+ Tfc-like cells rapidly gained a polyfunctional effector phenotype by producing the cytokines TNF-α, IFN-γ, and IL-2 after hours of PMA/ionomycin stimulation." (PMID 35443611, 2022). "CXCR5 expression in cell lines of human non-small cell lung carcinoma and small cell lung carcinoma (SW-1271) were evaluated by flow cytometry." (PMID 25271023, 2014). "Previous reports showed that, for non-small cell lung cancer (NSCLC) patients, the tumor sites express high levels of chemokine CXCL13, whereas CXCR5, the only receptor for CXCL13, is mainly expressed on B cells and follicle helper T cells." (PMID 34553036, 2021). "In non-small cell lung cancer (NSCLC), as the ligand of CXCR5, CXCL13 has been reported to be highly expressed in CD8+ lymphocyte populations with high PD-1 expression, which can attract other immune cells to TAIM and predict response to anti-PD-1 therapy strongly." (PMID 33763372, 2021).
osteosarcoma (8 papers, 2008 to 2025). A usually aggressive malignant bone-forming mesenchymal neoplasm, predominantly affecting adolescents and young adults. "The CXCL13:CXCR5 axis has also been implicated in the initiation and progression of other solid tumors, such as ovarian cancer, melanoma, oral squamous cell carcinoma, osteosarcoma, thyroid cancer, and neuroblastoma." (PMID 31354634, 2019). "Here, we report that the CXCL13/CXCR5 interaction promotes the migratory and invasive potential of human osteosarcoma cells, which in turn mediates the phospholipase C β (PLCβ), protein kinase C α (PKCα), c-Src, and nuclear factor-κB (NF-κB) pathways." (PMID 32847038, 2020). "A comparison of levels of CXCR5 protein expression in all three osteosarcoma cell lines demonstrated that CXCR5 expression correlates with malignancy." (PMID 32847038, 2020). "Based on the available data of CXCRs in osteosarcoma, we assessed the prognostic role of CXCR2, CXCR4, and CXCR5 expression in osteosarcoma." (PMID 31696204, 2019). "The Kaplan–Meier analyses were conducted to estimate the survival impact of expression of CXCR2, CXCR3, CXCR4, and CXCR5 in osteosarcoma." (PMID 31696204, 2019). "However, little is known about the CXCL13/CXCR5 signaling axis in osteosarcoma." (PMID 32847038, 2020). "In conclusion, the co-expression of CXCR5 and IL-7 in NKG2D-CAR-T cells holds promise for optimizing CAR-T cell therapy for osteosarcoma." (PMID 39450160, 2024). "Given the high expression of MICA/B and CXCL13, human osteosarcoma cell lines constitute the perfect avenue for studying our CAR system expressing NKG2D, CXCR5, and IL-7." (PMID 39450160, 2024). "Our study has identified that the CXCL13/CXCR5 axis facilitates VCAM-1 production and the migration of human osteosarcoma cells via the PLCβ, PKCα, c-Src, and NF-κB signaling pathways." (PMID 32847038, 2020). "Our study identified that CXCL13/CXCR5 axis facilitate VCAM-1 production and cell migration in human osteosarcoma via the phospholipase C beta (PLCβ), protein kinase C α (PKCα), c-Src, and nuclear factor-κB (NF-κB) signaling pathways." (PMID 32847038, 2020). "The clinical data from a total of 98 cases with osteosarcoma and the corresponding expression data of CXCR2, CXCR3, CXCR4, and CXCR5 were included." (PMID 31696204, 2019). "CCR1, CCR2, CCR5, CCR7, CXCR4, CXCR5 and CX3CR1 were found to be expressed in 100% of the osteosarcoma samples tested." (PMID 18215331, 2008). "Thus, in the case of osteosarcoma, CD44 and Nanog are outstanding markers when isolation is carried out with induction media, while markers such as ALDH and CXCR5 are found on biopsy samples." (PMID 37173919, 2023). "Here, we found that CXCR5 siRNA and CXCR5 antibody markedly inhibited CXCL13-induced VCAM-1 expression and cell migration, suggesting that the CXCL13/CXCR5 interaction regulates VCAM-1-mediated migration of human osteosarcoma cells." (PMID 32847038, 2020). "In addition, it was also found that the fraction of CD4+CXCR5+Tfh cells in patients with metastasis of osteosarcoma was greater than in patients without metastasis." (PMID 35494526, 2022). "Therefore, the CXCL13/CXCR5 interaction regulates VCAM-1 synthesis and osteosarcoma cell migration." (PMID 32847038, 2020). "In the present study, we observed that the expression of CXCR2, CXCR4, and CXCR5 were not correlated with the prognosis, but CXCR3 low expression was correlated with poor prognosis in osteosarcoma." (PMID 31696204, 2019).
AIDS (7 papers, 2010 to 2023). A syndrome resulting from the acquired deficiency of cellular immunity caused by the human immunodeficiency virus (HIV). "However, SIV and HIV infections and acquired immunodeficiency syndrome (AIDS) constitute excellent models for the study of CXCR5+CD8+ T cells due to the high compromise of follicle cells in this disease." (PMID 29085360, 2017). "CXCL13/CXCR5 are expressed, and may play a role, in some non-AIDS-associated B cell tumors." (PMID 21490903, 2010). "Our findings indicate that to specifically boost the function of PD-1+CXCR5+CD8+ T cells represent a novel therapeutic strategy for AIDS patients." (PMID 29312314, 2017). "The expression or function of CXCL13 and CXCR5 was examined on primary AIDS-NHL specimens or AIDS-NHL cell lines." (PMID 21490903, 2010). "In summary, we have demonstrated an association between expression of the chemokine, CXCL13, and its receptor, CXCR5, and AIDS-NHL." (PMID 21490903, 2010). "In the immunohistochemistry studies, all AIDS-NHL specimens showed expression of CXCR5, as did both AIDS-NHL cell lines." (PMID 21490903, 2010). "Furthermore, cells of AIDS-BL tumors growing in the mice showed greatly elevated surface expression of CXCR5." (PMID 23936541, 2013). "AIDS-NHL cell lines expressed CXCR5 and showed chemotaxis towards CXCL13." (PMID 21490903, 2010). "In this report, we define the expression and function of CXCL13 and CXCR5 in AIDS-NHL." (PMID 21490903, 2010). "A second possibility is that the CXCL13 and/or CXCR5 could be directly promoting AIDS-NHL tumor growth, or performing some other tumor-promoting functions, such as inhibiting apoptosis or enhancing angiogenesis." (PMID 21490903, 2010). "All primary AIDS-NHL specimens showed CXCR5 expression and most also showed CXCL13 expression." (PMID 21490903, 2010). "The receptor for CXCL13, CXCR5, appears to be commonly expressed in AIDS-NHL, as well." (PMID 21490903, 2010). "Additionally, the CXCR5 on the AIDS-NHL cell lines appeared to be functional, as both cell lines showed chemotaxis towards CXCL13." (PMID 21490903, 2010). "Although our studies show that both CXCL13 and CXCR5 are commonly expressed in AIDS-NHL, future studies will be needed to determine more exactly what roles these molecules may be playing in these cancers." (PMID 21490903, 2010). "All AIDS-NHL tumors showed some degree of CXCR5 expression, and most (22/24) expressed CXCL13." (PMID 21490903, 2010). "CXCL13/CXCR5 are expressed in AIDS-NHL and could potentially be involved in its biology." (PMID 21490903, 2010). "For these studies, we examined CXCR5 and CXCL13 expression in tissue arrays containing sections of primary specimens of AIDS-NHL from different subjects, using immunohistochemistry." (PMID 21490903, 2010). "Future studies will be needed to more fully determine the feasibility of using CXCL13 as a biomarker for AIDS-NHL, as well as to define the function of CXCL13 and CXCR5 in the pathogenesis of AIDS-NHL." (PMID 21490903, 2010). "In these studies, we examined expression of CXCR5 and CXCL13 on the AIDS-NHL cell lines, 2F7 (Burkitt subtype) and R (DLBCL subtype)." (PMID 21490903, 2010). "Given that AIDS-related NHL is frequently related with EBV infection, this CXCL13/CXCR5 interaction might be present in ENKTL like AIDS-related NHL." (PMID 25966773, 2015). "Several mechanisms, which are not necessarily mutually exclusive, appear possible: first, it seems plausible that CXCR5 and CXCL13 could be playing a role in the initial development of AIDS-NHL." (PMID 21490903, 2010). "Our studies do suggest that autocrine interactions could be occurring in AIDS-NHL, as some tumor cells appeared to express both CXCR5 and CXCL13 in both the immunohistochemistry and AIDS-NHL cell line studies (Section 3)." (PMID 21490903, 2010). "Furthermore, CXCR5 and/or CXCL13 were expressed in most primary AIDS-NHL tumor specimens." (PMID 23936541, 2013).
AIDS (continued). "The marked elevations in tumor cell CXCR5 expression and in murine CXCL13 levels seen in the model may potentially identify an important link between tumor-interacting histiocytes and tumor cells in AIDS-BL." (PMID 23936541, 2013).
asthma (7 papers, 2019 to 2024). "Studies to mechanistically understand biologics that target CCR2 and CXCR5 along with chronotherapeutic approaches will provide a new direction in the treatment of asthma." (PMID 37781650, 2023). "Of interest, one asthma‐specific SNP (rs12365699), near CXCR5 gene, showed a different direction of effect in the asthma population (risk allele was associated with higher AHR), whereas in the general population, this SNP was associated with lower AHR." (PMID 37186423, 2023). "RT-PCR analysis of PBMCs isolated from the asthma group and healthy controls showed a significant increase in the expression of CXCR5 mRNA of patients asthma (mean = 246 fold expression, P < 0.05) relative to normal controls (mean = 141)." (PMID 35165593, 2022). "This study was carried out to assess the plasma levels of CXCL13 chemokine and its receptor CXCR5 as potential biomarkers in asthma exacerbation." (PMID 35165593, 2022). "This study is aimed to evaluate plasma levels of CXCL13 and its receptor CXCR5 in Saudi patients with asthma exacerbation relative to healthy controls." (PMID 35165593, 2022). "CCR2 receptor regulates eosinophil and macrophage infiltration, and CXCR5 plays an important role during antibody maturation and class switching, which may be a key target for asthma therapy." (PMID 37781650, 2023). "Taken together, this finding suggests that CXCR5 may reduce IgE production and, therefore, can be useful for asthma treatment." (PMID 35165593, 2022). "Additionally, CXCR5 mRNA levels were higher in asthma exacerbation patients compared to healthy controls." (PMID 35165593, 2022). "Collectively, targeting CXCL13 or blocking CXCR5 may contribute to asthma treatment and reduce the severity of asthma." (PMID 35165593, 2022). "In addition, CXCR5 mRNA levels were elevated significantly in the asthma group than in the healthy controls." (PMID 35165593, 2022). "CXCR5 can also be expressed by follicular helper T (TFH) cells subset CXCR5+CD4+ T and played an essential role in enhancing IgE production in asthma." (PMID 35165593, 2022). "In human studies, our group and other groups have found significantly higher circulating TFH cell (CXCR5+CD4+) levels in both child and adult asthma patients in comparison with healthy cohorts." (PMID 31921177, 2019).
myasthenia gravis (7 papers, 2015 to 2024). Myasthenia gravis (MG) is a rare, clinically heterogeneous, autoimmune disorder of the neuromuscular junction characterized by fatigable weakness of voluntary muscles. "The formation of CXCL13/CXCR5‐derived tertiary lymphoid structures has been associated with the evolution of a divergent range of diseases, including MS, myasthenia gravis, Sjögren's disease, RA, bullous pemphigoid, Graves thyroiditis, and infectious diseases." (PMID 35702353, 2022). "A similar role of CXCL13 and/or CXCR5 in regulating the formation of ectopic lymphoid structures was subsequently found in myasthenia gravis, Sjögren's syndrome, and SLE." (PMID 35702353, 2022). "Current investigations have revealed that the percentage of CD4+CXCR5+Tfh to CD4+T cells in the PB of patients with myasthenia gravis is considerably greater than that of healthy controls and there is a positive correlation between the percentage and the stage of the disease." (PMID 35494526, 2022).